DUSP10 (dual specificity phosphatase 10)
Diseases named in the same sentence as DUSP10 in open-access papers (continued):
Sharing a sentence is not in itself a finding about the gene and the disease.
cancer (25 papers, 2018 to 2026). A tumor composed of atypical neoplastic, often pleomorphic cells that invade other tissues. "We employed the pan-cancer analysis of DUSP10 and detected that higher DUSP10 expression was linked to shorter survival time, higher ICPGs expression, and higher TMB burden in pan-LGG." (PMID 37387540, 2023). "LINC02257, an enhancer RNA with DUSP10 as the target gene, has been reported to be upregulated and associated with the survival outcomes in multiple kinds of cancers." (PMID 35846431, 2022). "Cancer progression is related to an uncontrolled cell division and DUSP10 overexpression produces the loss of cell-contact inhibition through the dephosphorylation of Yes-associated protein (YAP) at Ser397." (PMID 32410997, 2020). "Another SNP (rs6687758) located downstream of DUSP10 is associated with tooth agenesis, which in the family history of cancer positively correlated with a specific haplotype for this polymorphism." (PMID 30939861, 2019). "Additionally, GSEA analysis explicated that the high-DUSP10 subset was mainly linked to immune responses and cancer-associated signaling pathways." (PMID 37387540, 2023). "Recent research has revealed that elevated DUSP10 expression was strictly associated with the malignant development of several cancers, such as liver, colorectal, breast, and pancreatic cancers." (PMID 37387540, 2023). "In addition, DUSP10 can be induced by oxidative stresses such as H2O2 and binds to over-oxidized peroxiredoxin; this complex preserves the DUSP10 activity, leading to p38 inactivation and reducing cancer-associated senescence in BC." (PMID 30939861, 2019). "Several research have found elevated levels of DUSP10 messenger RNA in cancerous tissues, suggesting a cancer-promoting role." (PMID 40027133, 2025). "By contrasting the DUSP10 expression data of pan-cancer, we discovered that DUSP10 was aberrantly increased in diverse tumors, including LGG." (PMID 37387540, 2023). "Firstly, we initiated a pan-cancer analysis of DUSP10 and determined that the prognostic significance of DUSP10 in pan-LGG was more valuable than in other tumors." (PMID 37387540, 2023). "MiR-21, miR-30b, and miR-155 bind to the 3′-untranslated region of DUSP10 and inhibit the expression of DUSP10 in diverse cancer cells." (PMID 36713584, 2022). "The available data suggests that DUSP10 is a potent pro-tumorigenic and anti-inflammatory gene and therefore represents an attractive therapeutic target for the treatment of some cancers and inflammatory diseases." (PMID 30939861, 2019). "Particularly, DUSP10 is induced in many types of cancers, and its enhanced expression confers in general a pro-tumorigenic capacity to neoplastic cells for proliferation, migration, and differentiation." (PMID 30939861, 2019). "This suggests a complex role of DUSP10 on MAPKs regulation and, in consequence, its impact in a wide variety of responses involved in both cancer and inflammation." (PMID 30939861, 2019). "Here, we review DUSP10 function in cancerous and immune cells and studies in both mouse models and patients that establish a clear role of DUSP10 in different processes such as inflammation, immunity, and cancer." (PMID 30939861, 2019). "On the other hand, several research studies in cancer during the last years have reported DUSP10 upregulation in colon cancerous tissue and to a lesser extent in other cancers such as lung, breast, prostate, and glioblastoma." (PMID 30939861, 2019). "In fact, our analysis of available databases indicates that AML cells have the highest DUSP10 mRNA expression of all cancer types." (PMID 30939861, 2019). "On the other hand, different groups have described how the DUSP10 gene is negatively regulated by mirRNAs, which are induced in different diseases and cancers." (PMID 30939861, 2019). "A growing number of studies have elaborated that increased DUSP10 expression may promote the malignant progression of several cancers." (PMID 37387540, 2023).
cancer (continued). "Accumulating evidence shows that DUSP10 plays an important role in cancer progression." (PMID 36713584, 2022). "This study, for the first time, analyzed the role of DUSP10 across diverse cancer types." (PMID 36713584, 2022). "The protein subnetwork of PIK3R2 could be used for further pan-cancer studies in the future: DUSP10, DUSP6, FHL2, IRS2, PIK3R2, and RIPK2." (PMID 36329531, 2022). "The role of DUSP10 in cancer may be related to specific cancer types, some studies indicated that it is an oncogene, while in other studies indicated that it is a tumor suppressor." (PMID 34168991, 2021). "Until recently, there were few reports regarding the putative role of DUSP10 in cancer." (PMID 32410997, 2020). "Therefore, investigation into the role of DUSP10 in inflammation in cancer would be of great interest." (PMID 30939861, 2019). "Nonetheless, there are some studies assigning a suppressive role of DUSP10 in cancer." (PMID 30939861, 2019). "Below, we will summarize main studies about the presence of DUSP10 in cancer reported to date." (PMID 30939861, 2019). "Moreover, DUSP10 is a good anti-cancer and anti-inflammatory therapeutic target, but more studies are needed to elucidate its role in each specific cellular and physiological context." (PMID 30939861, 2019). "There have also been a few reports regarding the putative role of DUSP10 in cancer." (PMID 30939861, 2019). "However, further basic and clinical investigations in specific diseases would be required to determine the role of DUSP10 in cancer." (PMID 30939861, 2019). "Thus, DUSP10 might promote the malignant progression of LGG by activating the cancer-connected signaling pathways." (PMID 37387540, 2023). "However, in some cases, DUSP10 inflammation modulating activity may also suppress tumor development in an indirect way in some inflammation-driven cancers pointing our complex role of DUSP10 in cancer." (PMID 30939861, 2019). "In addition, the action of DUSP10 on cancer, inflammation, and immunity may take place through inactivation of its ‘classical’ targets p38 and JNK, but also through ERK or by directly targeting other proteins like IRF3 in a MAPK-independent manner." (PMID 30939861, 2019). "In another form of cancer (hepatocellular carcinoma), TP53INP1 downregulation has been shown to promote cancer metastasis through the DUSP10/ERK signaling pathway." (PMID 38201290, 2023). "DUSP10 is a stress-activated, JNK/p38-specific MKP widely expressed, reported to be involved in cancer progression and in the regulation of immune response." (PMID 30967582, 2019). "Interestingly, when considering TA in the presence of family history of cancer, positive association was found for carriers of a TT genotype (thus two copies of the minor allele T) in ATF1 rs11169552 (P = 0.00004), and for carriers of a GG genotype in DUSP10 rs6687758 (P = 0.003)." (PMID 29445242, 2018). "In addition, the dual-specificity protein phosphatase protein family (DUSP10/MKP-5, DUSP9/ MKP-4) shows antagonistic effects in cancer and fibrosis." (PMID 38730387, 2024). "Meanwhile, DUSP10 showed higher intratumoral than non-tumoral expression levels in patients with cancer." (PMID 37298537, 2023). "Thus, it has been identified by cDNA microarray analysis that DUSP10 expression is increased in primary cultures of human prostatic epithelial normal and cancer cells, but not in normal prostatic stromal cells, after 1,25D treatment." (PMID 30939861, 2019). "Again genes involved in other cancer-relevant processes such as cell proliferation, migration, differentiation, apoptosis, or cytoskeletal remodeling were among the driver candidates (all underexpressed with reduced copy number: ARHGAP18, DUSP10, PAK7, PDGFC, RNF217)." (PMID 31682594, 2019).
tumor (20 papers, 2014 to 2024). "A functional association of high nuclear DUSP10 levels with nuclear YAP1 expression was also observed in tumor cells of CRC patient samples." (PMID 31717606, 2019). "Specifically, strong nuclear DUSP10 staining was significantly associated with a higher tumor stage compared to weak nuclear DUSP10 staining, adjusted for age, gender, and chemotherapy." (PMID 31717606, 2019). "Moreover, we inspected the connection between DUSP10 expression and tumor mutation burden (TMB) in 33 types of tumors." (PMID 37387540, 2023). "We observed an association between DUSP10 expression and tumor stage." (PMID 31717606, 2019). "The downregulation of DUSP10 expression was deemed a tumor suppressor and correlated with tumor migration and distant metastasis." (PMID 37298537, 2023). "The results disclosed that DUSP10 expression was positively related to the ESTIMATE, stromal and immune scores but inversely linked to tumor purity in the TCGA and CGGA datasets." (PMID 37387540, 2023). "Taking into account that the TAF of DUSP10 amounted to 48%, and the tumor cell infiltration was 80%, indicates the possibilities of a driver oncogene in this relapse." (PMID 36037157, 2022). "Previous studies have pointed in the same direction that there is overall increase in patients’ relapse-free survival when DUSP10 expression is upregulated, and that DUSP10 mRNA was increased in the tumour compared with normal tissue adjacent to the tumours." (PMID 31821333, 2019). "Nuclear DUSP10 expression was correlated with high tumor stage and a poor prognosis in a large cohort of CRC patients." (PMID 31717606, 2019). "Most of those studies have found increased DUSP10 mRNA in tumor tissue, thus suggesting a pro-tumorigenic role for this phosphatase." (PMID 30939861, 2019). "Summarizing, DUSP10 expression has an essential role in controlling tumor development and inflammatory response through MAPKs or other novel and different targets." (PMID 30939861, 2019). "Each tumor sample was confirmed histologically, extracts prepared and the total relative abundance of DUSP10, phospho-Ser-473-AKT and phospho-Thr180/Tyr182-p38 expressed determined by Western analysis." (PMID 25568665, 2014). "Seventeen of 32 (53%) tumor samples exhibited markedly elevated DUSP10 expression, which we defined as greater then a 10-fold increase relative to mean levels expressed in normal brain." (PMID 25568665, 2014). "Thus, we entirely investigated the connection between DUSP10 expression, clinical features, prognosis, biological functions, tumor immunity, gene variations, and responses to immunotherapy/chemotherapy in LGG." (PMID 37387540, 2023). "Diverse studies have confirmed the high expression of DUSP10 in human tumor tissues." (PMID 36713584, 2022). "Additionally, the quantity of nuclear DUSP10 in CRC tumor biopsies is directly correlated with high tumor stage CRC and poor prognosis and survival in a large cohort of CRC patients, being also associated to high expression of nuclear YAP1." (PMID 32410997, 2020). "Strong nuclear DUSP10 staining also correlated with high tumor stage and poor survival." (PMID 31717606, 2019). "Moreover, modulating DUSP10 activity resulted in altered GBM tumor responses to PP242 and elevated DUSP10 expression was demonstrated in a significant number of GBM patient tumors." (PMID 25568665, 2014). "As our previous studies implicated sustained activation of the p38 signaling pathway in mTOR inhibitor resistance, we further tested whether alterations in DUSP10 activity would affect PP242 GBM tumor cell responses." (PMID 25568665, 2014). "Therefore, we estimated the connection between DUSP10 expression and immunological traits (including stromal and immune scores, tumor-infiltrating immune cells [TIICs], and immune checkpoint genes [ICPGs] expression), genomic alternations, and responses to immunotherapy/chemotherapy." (PMID 37387540, 2023).
tumor (continued). "Finally, Klf4 and Egr1 levels were lower in the CTCs containing Parsortix-isolated samples, while Dusp10 and Pmepa1 higher levels in these samples could indicate tumor presence." (PMID 35153760, 2021). "However, DUSP10 in most of the cancerous tissues has higher expression levels than that corresponding to normal tissue, although there is variability depending on the tumor type and even within a tumor type." (PMID 30939861, 2019). "We found a cohort of genes that were nonspecific and had broad expression in other cell types in both normal and tumor contexts, including SLC39A14 and DUSP10." (PMID 35687691, 2022). "Among tumor-related genes (CXCR4, FOS, DUSP10), FOS is a member of the FOS gene family and plays a regulatory role in cell proliferation, differentiation, and apoptosis." (PMID 35111153, 2021). "Our results suggest that B7-H3 suppresses the expression of DUSP10 at the mRNA level, which in turn leads to higher p38 MAPK activation and increases tumor cell resistance to chemotherapy." (PMID 30967582, 2019). "Conversely, in tumors derived from the phosphomimetic DUSP10 overexpressing cells, PP242 treatment markedly reduced tumor size, increased apoptotic induction, blunted p38 signaling and increased DUSP10 expression." (PMID 25568665, 2014). "On the other hand, the variable effects of JNK and p38 MAPKs on NB cell apoptosis endorse the possibility of a beneficial use of inhibitors of JNK- or p38-specific MKPs, such as DUSP1, DUSP8, DUSP10, or DUSP16, but only in NB cases in which the activity of JNKs or p38s favors tumor chemosensitivity." (PMID 30866462, 2019). "Furthermore, dual‐specificity phosphatase 10 (DUSP10, MKP5) and downregulated FBP1 expression in drug‐resistant NSCLC tumor cell lines were observed among the three datasets." (PMID 31025554, 2019). "In tumor cells overexpressing the nonphosphorylatable DUSP10 mutant xenografts, growth was modestly enhanced by PP242 treatment." (PMID 25568665, 2014). "We found DUSP10 and YAP1 expression higher in tumor samples than normal tissue, but not of p-p38 in most tumor samples." (PMID 31717606, 2019). "DUSP10 is most likely dysregulated by HBV, but it does not appear to be dysregulated in a comparison between tumor samples from drinkers with HBV infection and normal samples from drinkers." (PMID 31480259, 2019).
infection (9 papers, 2013 to 2023). The state of being infected such as from the introduction of a foreign agent such as serum, vaccine, antigenic substance or organism. "Infection with either strain of RV caused a similar regulation of DUSP10 expression, with an initial increase followed by a consistent and significant downregulation at 8 h postinfection before a return to baseline by 24 h." (PMID 30333178, 2019). "This implies specific roles for DUSP10 in individual pathogenic infections, potentially consequent upon differential TLR signaling by each virus." (PMID 30333178, 2019). "Infection of COPD PBECs with RV1B caused a pattern of change in expression of DUSP10 mRNA and protein similar to that seen for normal PBECs, with an initial increase followed by a downregulation by 8 h." (PMID 30333178, 2019). "Finally, the role of DUSP10/MKP-5 in susceptibility to infection with LCMV and to MOG-induced EAE was tested." (PMID 30401534, 2019). "The use of Dusp10-deficient mice allowed the elucidation of the role of this phosphatase on the regulation of immunity and inflammation, demonstrating that it plays an essential non-redundant role in regulating some aspects of immune function against infections and other diseases." (PMID 30939861, 2019). "Herein, we infected Raw264.7 macrophages with BCG at MOI 10 and detected the expression levels of mmu-miR-25-3p, DUSP10 mRNA, and DUSP10 protein by qRT-PCR and Western blotting at 0, 1, 4, 8, 12, 24, 48, and 72 h post-infection." (PMID 37256106, 2023). "Compared to the blank group, the expression trend of mmu-miR-25-3p showed a peak expression at 4 h after BCG infection (p < 0.05), while the expression trend of DUSP10 mRNA was significantly downregulated between 1 and 12 h post-infection (p < 0.05)." (PMID 37256106, 2023). "Compared to the blank group, the expression level of DUSP10 protein was continuously downregulated after infection (p < 0.05)." (PMID 37256106, 2023). "This identifies DUSP10 as a central regulator of the inflammatory response to respiratory viruses: infection of epithelial cells induces release of IL-1β, which acts back on the epithelium to promote inflammation, which is negatively regulated by DUSP10." (PMID 30764493, 2019). "In accordance with previous results, infection of PBECs with RV14 led to a small increase in CXCL8 release which was unaffected by DUSP10 knockdown." (PMID 30333178, 2019). "In response to infection of THP-1 cells with Porphyromonas gingivalis, a common pathogen associated with chronic adult periodontal disease, DUSP10 expression is decreased." (PMID 30939861, 2019). "Interestingly, DUSP10 knock out mice also had decreased viral titres and better survival in response to infection." (PMID 30764493, 2019). "Thus, after infection, injury, disease induction, or treatment with several stimuli, DUSP10 can be upregulated or downregulated resulting in different cellular and molecular outcomes, leading to decreased or increased inflammation respectively." (PMID 30939861, 2019). "Infection with either strain of RV caused decreases in DUSP10 expression at the mRNA and protein levels which were not seen in response to IL-1β." (PMID 30333178, 2019). "The infection of BCG induced the upregulation of mmu-miR-25-3p and downregulation of DUSP10 in RAW264.7 cells, which further increased the expression of LC3-II and promoted autophagy." (PMID 37256106, 2023). "Similar, in the chicken, DUSP1, DUSP5, DUSP7, DUSP10, DUSP15, and DUSP16 were significantly downregulated in response to infection." (PMID 36683094, 2023). "DUSP10 protein expression followed a similar pattern, with a slight increase 2 h following RV1B infection before a decline to a level below the baseline." (PMID 30333178, 2019).
infection (continued). "The protein product of DUSP10 preferentially binds to the stress-activated p38 MAPK (mitogen-activated protein kinase) and plays an important role in regulating chemokine induction after infection by various pathogens, and in coordinating MAPK activity in response to oxidative stress." (PMID 23936387, 2013). "Reduced DUSP10 levels potentiate the production of CXCL8 and CXCL1 but not IFN-β production in response to infection or IL-1β alone." (PMID 30939861, 2019).
inflammation (1 paper, 2018). Aberrant reaction of the microcirculation characterized by movement of fluid and leukocytes from the blood into extravascular tissues. "We then administered IL-33 to these mice intranasally and monitored development of airway inflammation after transfer of Dusp10-sufficient and Dusp10-deficient Tpath2 cells." (PMID 30315197, 2018). "Hence, Dusp10-overexpressing ILC2s were rendered unable to induce eosinophilic airway inflammation induced by papain administration." (PMID 30315197, 2018).
DUSP10 also shares sentences with these, for which no sentence is quoted: Insulin resistance (5 papers); diabetes (3); cardiac disease (2); cardiac hypertrophy (2); muscular dystrophy (2); bacterial infection (1); breast tumors (1); cardiomyopathy (1); cardiovascular disease (1); cognitive deficits (1); colitis (1); diffuse large B-cell lymphoma (1); esophagus cancer (1); fibrosis (1); Glucose intolerance (1); heart failure (1); Hepatic steatosis (1); Hypertension (1); Impaired glucose tolerance (1); liver (1); Myocardial fibrosis (1); osteoarthritis (1); progressive supranuclear palsy (1); prostate carcinoma (1); rectum adenocarcinoma (1); schizophrenia (1); steatosis (1); type 2 diabetes mellitus (1).